IL6 (interleukin 6)
Diseases named in the same sentence as IL6 in open-access papers (continued):
Sharing a sentence is not in itself a finding about the gene and the disease.
osteoarthritis (continued). "The aim of this work is to compare the expression profile of IL-15Ralpha, its ligand IL-15 and two validated cytokines targets in RA, TNF alpha and IL-6, in SF from RA regards to Osteoarthritis (OA) patients." (PMID 25879761, 2015). "It is unclear why the concentration of these cytokines was reduced in SNS-gp130−/− mice but the levels of CGRP, substance P and IL-6 are elevated in serum and synovial fluid of RA and osteoarthritis patients." (PMID 26590032, 2015). "Remarkably, the levels of these neuropeptides and IL-6 were shown to be enhanced in serum and synovial fluid of RA and osteoarthritis patients." (PMID 26590032, 2015). "Along this line of evidence, IL-17 was shown to enhance TNF-induced synthesis of IL-1, IL-6 and IL-8 by normal skin fibroblasts and osteoarthritis fibroblast-like synoviocytes." (PMID 24289089, 2013). "In RA patients as well as in arthritic animals, IL-6 concentration in serum and synovial fluid is higher than in healthy individuals or patients with osteoarthritis." (PMID 22546471, 2012). "Increasing evidence suggests that IL-6 and its soluble receptor are involved in both inflammatory and degenerative joint diseases." (PMID 21682897, 2011). "This is in agreement with an animal study that reported an increase in markers of osteoarthritis in dogs with acetabular dysplasia (including IL-1β, IL-6, tumor necrosis factor (TNF)-alpha, and matrix metalloproteinase (MMP)-3) in comparison to normal dogs." (PMID 20367415, 2010). "Furthermore, CRP, IL-6, and TNF-α were found to be reduced by resistance and neuromuscular training in osteoarthritis (OA) patients with pain caused by physical dysfunction." (PMID 41598488, 2026). "Additionally, it significantly inhibited NO production by 66% using a whole blood assay and IL-6 expression in primary human osteoarthritis chondrocytes." (PMID 41293417, 2025). "Co2+ stimulates the secretion of TNF-α and IL-6 from osteoarthritis fibroblasts." (PMID 41036386, 2025). "Genes associated with osteoarthritis, DDH, and FAI include COL1A1, MMP13, and IL-6." (PMID 41019141, 2025). "GLP-1 RAs such as liraglutide, exenatide, lixisenatide, dulaglutide, and geniposide share common chondroprotective mechanisms in osteoarthritis, including suppression of NF-κB (reducing IL-6, TNF-α, and COX-2), inhibition of matrix-degrading enzymes (MMP-3/13, ADAMTS-4/5), and attenuation OS." (PMID 41158135, 2025). "Moreover, gut microbiota metabolites can influence the function of local T and B cells in joints, modulating the production of inflammatory factors such as TNF–α and interleukin 6 (IL-6), which are key in the osteoarthritis pathological process." (PMID 40431441, 2025). "Additionally, IL-6 levels positively correlate with radiographic severity and progression of osteoarthritis." (PMID 41019141, 2025). "Interleukin-6 level was greater in patients with degenerative joint disease with disc displacement." (PMID 41164068, 2025). "Similarly, in MIA-induced osteoarthritis rat models, Rb1 (10 mg/kg) administration for 2 weeks improved joint histology, suppressed pro-inflammatory cytokines (e.g., IL-1β and IL-6), and enhanced chondrocyte viability." (PMID 40507179, 2025). "In addition, both cell lines can produce the three main pro-inflammatory cytokines that are significantly elevated in osteoarthritis patients, namely, IL-1β, IL-6, and TNF-α." (PMID 39204123, 2024). "Given that activated immune cells express RANKL, which is linked to osteoarthritis aggravation, we investigated whether ASC-expressed IL-6 could modulate RANKL expression." (PMID 39768138, 2024). "Additionally, ferulic acid, another HY-LL component, has been found to mitigate osteoarthritis chondrocyte toxicity by inhibiting the production of IL-6, PGE-2, and sub-MMP-9 and activating the SIRT1/AMPK/PGC-1α signaling pathway." (PMID 39337919, 2024).
osteoarthritis (continued). "Research has shown that golden buckwheat extract could delay the development of inflammation in rats with osteoarthritis of the knee by inhibiting the production of IL‐1β, TNFα, and IL‐6." (PMID 39139945, 2024). "Our results suggest that IL-6 high ASCs may offer greater therapeutic benefits in osteoarthritis by not only promoting tissue regeneration but also by suppressing key factors like RANKL that drive bone resorption." (PMID 39768138, 2024). "Furthermore, a PEMF can attenuate the progression of osteoarthritis in a murine model through the inhibition of TNF-α and IL-6 signals, which are crucial pro-inflammatory cytokines in the pathogenesis of osteoarthritis." (PMID 38731168, 2024). "The levels of IL-6 were elevated in patients with osteoarthritis (OA)." (PMID 36875034, 2023). "LncRNA FER1L4 governed the expression of IL-6 and regulated osteoarthritis in chondrocyte cells." (PMID 37779916, 2023). "However, some studies also showed that IL-6 levels were elevated in joints with symptomatic cartilage defects or osteoarthritis compared to healthy joints." (PMID 38107476, 2023). "Notably, about 50% of individuals with osteoarthritis endure synovitis, a significant contributor to IL-6 production in the condition." (PMID 38107476, 2023). "As inflammatory activity is critical to the pathogenesis of osteoarthritis, determining whether the FOSL2 regulon contributed to osteoarthritis-associated inflammation via IL-6, or other immunity-related genes, warrants further study." (PMID 36793138, 2023). "Tumor necrosis factor (TNF), interleukin-6 (IL-6), and in particular interleukin-1 (IL-1) are the pro-inflammatory cytokines that can activate the production of inflammatory and catabolic factors, speeding up the progression of osteoarthritis." (PMID 37893118, 2023). "The role of IL-6 in osteoarthritis (OA) is still controversial." (PMID 37919719, 2023). "Indeed, TSP2 is reportedly involved in inflammation during the pathogenesis of osteoarthritis by promoting interleukin-6 production in synovial fibroblasts via the PI3K/AKT/NF-κB pathway." (PMID 36344733, 2022). "Moreover, blockade of IL-6 in vivo in mouse models of osteoarthritis (OA) has been shown to be chondroprotective." (PMID 35039652, 2022). "The increased level of IL-6 after the 21-day rehabilitation program may reflect its anti-inflammatory effect in osteoarthritis patients subjected to prior hip or knee replacement surgery." (PMID 35625533, 2022). "Consistent with reports showing IL-6 knockout mice are prone to osteoarthritis also suggesting a homeostatic function of this cytokine, the increase in IL-6 in the NP of N153S mice may imply a stress or compensatory response to maintain disc homeostasis." (PMID 35769461, 2022). "It is known that IL-6 is seen at higher levels in osteoarthritis." (PMID 36078455, 2022). "A previous study demonstrated that dexamethasone had a chondroprotective effect, that is, it ameliorated arthritic pain and protected cartilage from damage in a rabbit osteoarthritis model via suppressing several pro-inflammatory gene markers, including il-1b, il-8, il-6, tnf-α, mmp-3, and mmp-13." (PMID 36429168, 2022). "We previously explained that IL-6 is also increased following sleep insufficiency, and thus may represent a possible mechanism by which sleep affects the pathogenesis of osteoarthritis." (PMID 36078455, 2022). "Levels of interleukin-6 (IL-6) and tumor necrosis factor-α (TNF-α), both key pro-inflammatory cytokines that induce cartilage catabolism, are elevated in OA patients (Chow and Chin, 2020; Osteoarthritis linked to higher parkinson’s disease risk, 2021)." (PMID 36419937, 2022). "The increased level of IL-6 after the rehabilitation may reflect its anti-inflammatory effect in osteoarthritis patients." (PMID 35625533, 2022).
osteoarthritis (continued). "Tumor necrosis factor (TNF) may play an important role in the inflammatory responses that occur during osteoarthritis, triggering the production of IL-6, IL-8, and RANTES by human articular chondrocytes." (PMID 36362117, 2022). "Inhibited pathways included leukocyte extravasation signaling, IL-6 across the time course, IL-15 production and acute phase response signaling, key players in the development and maintenance of synovitis and degenerative processes observed in osteoarthritis." (PMID 34956173, 2021). "Nobiletin suppressed IL-1β-induced proinflammatory mediators, including prostaglandin E2, nitric oxide, cyclooxygenase-2, inducible nitric oxide synthase, tumor necrosis factor-a, and IL-6 by inhibiting Akt and NF-κB activation in human osteoarthritis chondrocytes." (PMID 34066937, 2021). "Additionally, chondrocytes also secret pro‐inflammatory cytokines including IL‐6 and other inflammatory regulators during osteoarthritis progression resulting in disrupted homeostasis of the cartilage." (PMID 34078001, 2021). "IL-6, a pro-inflammatory marker, is involved in the disease progression of osteoarthritis." (PMID 34627160, 2021). "Therefore, inhibiting the expression of inflammation related genes IL-6, IL-1 β, and IL-18 is beneficial for the remission of osteoarthritis." (PMID 34421623, 2021). "Low innate production of interleukin (IL)-6 has been shown to be associated with the absence of osteoarthritis in old age." (PMID 31935848, 2020). "Interestingly, a preclinical study has shown that an EVOO-enriched diet had the best results on the musculoskeletal system in an osteoarthritis rat model, including decreased IL-6 expression." (PMID 33023123, 2020). "However, expression of these cytokines in osteoarthritis pain remains unresolved, and different studies have arrived at conflicting conclusions regarding interleukin 1β (IL-1β), interleukin 6 (IL-6) and tumor necrosis factor (TNF-α)." (PMID 32059658, 2020). "A significant increase of IL-6 and IL-8 has been observed in patients with osteoarthritis." (PMID 32189997, 2020). "The purpose of this study was to investigate the influence of moderate physical activity (MPA) on the expression of osteoarthritis (OA)-related (IL-1β, IL-6, TNF-α, MMP-13) and anti-inflammatory and chondroprotective (IL-4, IL-10, lubricin) biomarkers in the synovium of an OA-induced rat model." (PMID 30691048, 2019). "Inflammatory cytokines, including IL-1β, TNFα, and IL-6, play a key role in osteoarthritis, and IL-6 is considered to be the key cytokine; its effect is mainly based on promoting the formation of osteoclasts and bone resorption while synergism with IL-1β and TNFα." (PMID 31139654, 2019). "Pro-inflammatory cytokines such as IL-6 and TNF-α levels are elevated in the synovial fluid and cartilage of patients with osteoarthritis and chronic elevations in cytokines are associated with an increased risk of osteoarthritis." (PMID 30871193, 2019). "IL-6 expression was increased in osteoarthritis synovial membranes and synovial fluid, histone hyperacetylation, and DNA hypomethylation in the promoter of IL-6 gene were observed in osteoarthritis synovial fibroblasts compared with healthy synovial fibroblasts." (PMID 31139654, 2019). "IL-6 is also reported to exert a proinflammatory role in degenerative joint disease." (PMID 25888873, 2015). "In particular, they reported that IL-6 plays a major role in the development of osteoarthritis." (PMID 25662545, 2015). "Targeting multiple cytokines, including IL-6, may be effective in improving cartilage repair in symptomatic cartilage defects and osteoarthritis." (PMID 23206933, 2012). "In contrast, in osteoarthritis FLSs only one gene, that for IL-6, was modulated." (PMID 15642131, 2005).
osteoarthritis (continued). "Osteoarthritis (OA) is a degenerative musculoskeletal disorder marked by progressive cartilage degradation, synovial inflammation and subchondral bone remodeling, driven by pro-inflammatory mediators such as interleukin-6 (IL-6) and tumor necrosis factor-alpha (TNF-α)." (PMID 41623825, 2025). "Indeed, IL‐1β and IL‐6 were shown to induce ADAMTS5 expression in osteoarthritis." (PMID 40164572, 2025). "Interleukin-6 (IL-6) expression in mesenchymal stem cells (MSCs) has been shown to play a pivotal role in modulating cartilage regeneration and immune responses, particularly in the context of diseases that involve both degenerative processes and inflammation, such as osteoarthritis (OA)." (PMID 39768138, 2024). "Mechanistically, these anti-osteoarthritis effects were associated with upregulated expression of COL2A1 and aggrecan in the articular cartilage, along with a decrease in inflammatory mediators (NO, PGE2), cytokines (IL-6, IL-1, TNFα), and cartilage-degrading enzymes (MMP-3 and MMP-13) in serum." (PMID 39519204, 2024). "Nesfatin-1 has been shown to influence the production of pro-inflammatory mediators, e.g. COX-2, IL-6 and IL-8 in human primary chondrocytes in patients with osteoarthritis; it may play a role in pathogenesis or osteoarthritis, although the exact pathogenesis remains undefined." (PMID 38516409, 2024). "Pro-inflammatory cytokines such as TNFα, IL-1β, and IL-6 accelerate the aging process of mesenchymal stem cells, impairing their ability to differentiate into other cells and subsequently alter osteochondral homeostasis in the elderly population, leading to osteoarthritis." (PMID 38201942, 2023). "Patients with degenerative joint disease, when exposed to leptin, respond by producing proinflammatory cytokines such as IL-8, IL-6, and TNF-alpha, which may intensify the catabolism of proteoglycans, increase the expression of metalloproteinases (MMP), and thereby stimulate cartilage degradation." (PMID 38203376, 2023). "Interleukin-6 (IL-6) has historically been characterized as pro-inflammatory and documented to be upregulated in joints with osteoarthritis, although more recent work has suggested that it may play a more immunomodulatory and not strictly a pro-inflammatory role." (PMID 36876001, 2023). "Besides, IL-6 is well known for its contribution to progression of osteoarthritis." (PMID 32189997, 2020). "Higher IL-6 release from T98G when triggered by OA-CSF, in the presence of LPS, suggest the presence of “unknown molecule” in CSF that may be crucial in the maintenance phase of chronic pain in our osteoarthritis population." (PMID 32213162, 2020). "In the present study, we investigated the role of IL-6 in osteoarthritis (OA) patients and the effects of the stilbenoids monomethyl pinosylvin and pinosylvin on the expression of the cartilage matrix components aggrecan and collagen II and the inflammatory cytokine IL-6 in human OA chondrocytes." (PMID 30597965, 2018). "Osteoarthritis (OA) may be a response to superfluous mechanical stress or inflammation, and pro-inflammatory factors, including interleukin-1 (IL-1β), interleukin-6 (IL-6), and tumour necrosis factor-α (TNF-α), are involved in OA pathogenesis." (PMID 30286747, 2018). "This was done by analyzing the inflammatory cytokines (TNF-α, IL-1β, and IL-6), performing hematoxylin & eosin (H&E) staining and safranin O-fast green staining of the articular structures of the knee joint to investigate the effects of ChondroT in collagenase-induced osteoarthritis rat model." (PMID 29673343, 2018). "However, we are unaware of any study that has addressed the question whether elevated serum Shh and IL-6 levels correlates with bone metastasis and osteoarthritis." (PMID 28496132, 2017).
osteoarthritis (continued). "Osteoarthritis (OA) is characterized by the accumulation of chondrocytes expressing p16INK4a and markers of the senescence-associated secretory phenotype (SASP), including the matrix remodeling metalloproteases MMP1/MMP13 and pro-inflammatory cytokines interleukin-8 (IL-8) and IL-6." (PMID 24572376, 2014). "In the present study, we aimed to address the hypothesis by measuring the simultaneous levels of YKL-40 in plasma and in synovial fluid as well as to investigate whether YKL-40 in SF is associated with inflammatory and catabolic factors MMP-1, MMP-3, IL-6, and IL-17 in patients with osteoarthritis." (PMID 25132728, 2014). "This study aimed to determine whether, as in osteoarthritis, increased levels of interleukin-6 (IL-6) are present in the synovial fluid of patients with symptomatic cartilage defects and whether this IL-6 affects cartilage regeneration as well as the cartilage in the degenerated knee." (PMID 23206933, 2012). "Chlorogenic acid reversed the reduction in collagen II and the increase in iNOS/NO, IL-6, MMP-13, and COX-2/PGE2 levels in IL-1β-induced human SW-1353 chondrocytes, an in vitro model of osteoarthritis." (PMID 41515347, 2025). "Increased levels of IL-1β, IL-6, TNF-α, and PGE2 were reported in synovial fluid samples from patients with TMD, particularly in cases with degenerative joint disease and internal derangement." (PMID 40649748, 2025). "The expression of inflammatory biomarkers MyD88, p-IκBα, NF-κB, IL-6, IL-1β, and TNF-α in synovial fluid was lower in the curcumin-treated group compared to osteoarthritis rat groups." (PMID 40507179, 2025). "Conversely, GLP-1 analogs reduced IL-6 in other contexts: exendin-4 in LPS-stimulated macrophages, LIRA in osteoarthritis, and hepatic ischemia–reperfusion in male mice." (PMID 41304982, 2025). "Chronic obstructive pulmonary disease, biliary cirrhosis, cholangitis, and osteoarthritis exhibit overlapping detrimental SASP profiles, characterized by the presence of interleukin-6 (IL-6), interleukin-8 (IL-8), and matrix metalloproteinase (MMP)." (PMID 40041912, 2025). "In this study, we also observed that in the osteoarthritis model, the levels of TNF-α, IL-1β, and IL-6 were significantly elevated." (PMID 39754163, 2025). "Our findings indicate that Pioglitazone mitigates chondrocyte inflammation and osteoarthritis in murine models by inhibiting the expression of inflammatory mediators such as TNF‐α, IL‐6 and PGE2, and by preventing the degradation of aggrecan and collagen II." (PMID 40008494, 2025). "BM-MSCs display anti-inflammatory effect by reducing IL-6, TNF-α and NF-κB, while there were increased levels of IL-10 in osteoarthritis patients." (PMID 40839685, 2025). "Low-grade inflammation is common in patients with osteoarthritis (OA), and several pro-inflammatory markers, such as interleukin-6 (IL-6) and C-reactive protein (CRP), have been identified as independent predictors of the development of osteoarthritis." (PMID 40257716, 2025). "Previous studies have shown that RO 3306 suppresses osteoarthritis-related inflammation by reducing MMP-13 and IL-6 expression in chondrocytes and synovial fibroblasts." (PMID 41409278, 2025). "The active component harpagoside has been shown to suppress the expression of IL-6 and MMP13 in primary human osteoarthritis chondrocytes." (PMID 39519204, 2024). "For example, the serum levels of inflammatory cytokines, including IL-6, IL-13, and TNF-α, were significantly elevated in patients with osteoarthritis secondary to meniscus injury." (PMID 39330256, 2024). "Among these, monocyte chemoattractant protein 1 (MCP-1), interleukin 1 (IL-1), IL-6, MMP-3, and MMP-13 have been proposed as key mediators of the inflammation that characterizes osteoarthritis." (PMID 39335461, 2024). "IL-1β, IL6, and TNF-α induce chondrolysis, leading to arthralgia and/or the progression of osteoarthritis." (PMID 39850191, 2024).